POLR2M (RNA polymerase II subunit M)
Description:
[Isoform 1]: Appears to be a stable component of the Pol II(G) complex form of RNA polymerase II (Pol II). Pol II synthesizes mRNA precursors and many functional non-coding RNAs and is the central component of the basal RNA polymerase II transcription machinery. May play a role in the Mediator complex-dependent regulation of transcription activation. Acts as a negative regulator of transcriptional activation; this repression is relieved by the Mediator complex, which restores Pol II(G) activator-dependent transcription to a level equivalent to that of Pol II.
Synonyms: GRINL1A; Gdown; Gdown1
Tractability: PROTAC: ubiquitination databases record sites on it; its protein half-life has been measured.
Gene: Protein-coding gene on chromosome 15 (57,706,695 to 57,782,762, forward strand). Ensembl gene ENSG00000255529.
Subcellular location: Nucleus (Isoform 1)
Subcellular location (Human Protein Atlas): Nucleoplasm
Gene Ontology:
Molecular function: RNA polymerase II complex binding; transcription elongation factor activity
Biological process: transcription elongation by RNA polymerase II; transcription initiation at RNA polymerase II promoter; maintenance of ER location
Cellular component: nuclear envelope; nucleus; RNA polymerase II, core complex; transcription preinitiation complex; I band; neuronal cell body
Genetic constraint (gnomAD): Loss-of-function variants: 29 observed, 31.29 expected, observed/expected ratio (o/e) 0.93, 90% interval 0.69 to 1.26. The upper end of that interval is the gene's LOEUF score, 1.26, which puts it in group 5 of 6, group 1 being the genes least tolerant of losing a copy. Missense variants: 409 observed, 417.53 expected, observed/expected ratio (o/e) 0.98, 90% interval 0.9 to 1.06. Synonymous variants: 145 observed, 152.13 expected, observed/expected ratio (o/e) 0.95, 90% interval 0.83 to 1.09.
Homologues: Orthologues: rabbit POLR2M (77% identical), pig POLR2M (75% identical), mouse Polr2m (72% identical), rat Polr2m (72% identical), guinea pig POLR2M (58% identical), tropical clawed frog polr2m (34% identical), zebrafish polr2m (30% identical). Paralogues in human: MYZAP (14% identical), TUFT1 (8% identical), CCDC68 (7% identical).
Diseases named in the same sentence as POLR2M in open-access papers:
POLR2M is named in the same sentence as 7 diseases in open-access papers, as found by Europe PMC text mining. Sharing a sentence is not in itself a finding about the gene and the disease. The quoted sentences say what the papers report.
acute myeloid leukemia (1 paper, 2025). Acute myeloid leukemia (AML) is a group of neoplasms arising from precursor cells committed to the myeloid cell-line differentiation. "Although the polymerase subunit POLR2M showed favorable prognosis (OS) for CCC in our cohort, it has been found to be associated with poor prognosis in acute myeloid leukemia by silencing the MIR139 tumor suppressor." (PMID 40778374, 2025).
leukemia (1 paper, 2022). A malignant (clonal) hematologic disorder, involving hematopoietic stem cells and characterized by the presence of primitive or atypical myeloid or lymphoid cells in the bone marrow and the blood. "Furthermore, our findings reveal a PRC2-dependent POLR2M-mediated silencing mechanism of the MIR139 tumor suppressor in MLL-AF9 leukemia." (PMID 34741119, 2022).
POLR2M also shares sentences with these, for which no sentence is quoted: tumor (3 papers); chronic myelogenous leukemia (1); colon tumor (1); keratoconus (1); Recessive Dilated Cardiomyopathy (1).